RDH11 (retinol dehydrogenase 11)
Description:
Retinol dehydrogenase with a clear preference for NADP. Displays high activity towards 9-cis, 11-cis and all-trans-retinol, and to a lesser extent on 13-cis-retinol. Exhibits a low reductive activity towards unsaturated medium-chain aldehydes such as cis -6-nonenal and no activity toward nonanal or 4-hydroxy-nonenal. Has no dehydrogenase activity towards steroid.
Synonyms: RalR1; ARSDR1; PSDR1; SDR7C1; MDT1; CGI82; HCBP12; RDJCSS; SCALD
Tractability: Antibody: UniProt predicts a signal peptide or a membrane-spanning region. PROTAC: ubiquitination databases record sites on it; its protein half-life has been measured.
Gene: Protein-coding gene on chromosome 14 (67,676,800 to 67,695,793, reverse strand). Ensembl gene ENSG00000072042.
Subcellular location: Endoplasmic reticulum membrane
Pathways (Reactome):
Sensory Perception: Retinoid metabolism and transport; The canonical retinoid cycle in rods (twilight vision)
Signal Transduction: RA biosynthesis pathway
Gene Ontology:
Molecular function: 11-cis-retinol dehydrogenase (NADP+) activity; all-trans-retinol dehydrogenase (NADP+) activity; protein binding; all-trans-retinol dehydrogenase (NAD+) activity; oxidoreductase activity, acting on the CH-OH group of donors, NAD or NADP as acceptor; alcohol dehydrogenase (NADP+) activity; aldehyde dehydrogenase (NADP+) activity
Biological process: cellular detoxification of aldehyde; retinal metabolic process; retinoid metabolic process; retinol metabolic process; visual perception
Cellular component: endoplasmic reticulum membrane; photoreceptor inner segment
Genetic constraint (gnomAD): Loss-of-function variants: 15 observed, 25.57 expected, observed/expected ratio (o/e) 0.59, 90% interval 0.39 to 0.9. The upper end of that interval is the gene's LOEUF score, 0.9, which puts it in group 3 of 6, group 1 being the genes least tolerant of losing a copy. Missense variants: 286 observed, 324.13 expected, observed/expected ratio (o/e) 0.88, 90% interval 0.8 to 0.97. Synonymous variants: 131 observed, 136.81 expected, observed/expected ratio (o/e) 0.96, 90% interval 0.83 to 1.11.
Homologues: Orthologues: chimpanzee RDH11 (99% identical), macaque RDH11 (98% identical), dog RDH11 (89% identical), rabbit RDH11 (89% identical), pig RDH11 (85% identical), mouse Rdh11 (85% identical), guinea pig RDH11 (82% identical), rat Rdh11 (81% identical), zebrafish rdh12 (63% identical). Paralogues in human: RDH12 (71% identical), WWOX (39% identical), RDH16 (25% identical), HSD17B6 (25% identical), HSD17B11 (24% identical), RDH5 (24% identical), SDR9C7 (24% identical), SDR16C5 (23% identical), DHRS9 (22% identical), HSD17B13 (22% identical), HSD11B2 (21% identical), HSD17B2 (21% identical), and 13 more.
Diseases named in the same sentence as RDH11 in open-access papers:
RDH11 is named in the same sentence as 16 diseases in open-access papers, as found by Europe PMC text mining. Sharing a sentence is not in itself a finding about the gene and the disease. The quoted sentences say what the papers report.
prostate carcinoma (3 papers, 2005 to 2016). A carcinoma that arises from epithelial cells of the prostate gland. "RDH11 gene was initially known as prostate short-chain dehydrogenase 1 (PSDR1) since it was first discovered in a prostate cancer cell line after exposure to androgen." (PMID 27879662, 2016). "Genes over-expressed in prostate cancer include AMACR, HPN, RDH11, and TMPRSS2." (PMID 16638148, 2006).
retinitis pigmentosa (2 papers, 2018 to 2021). Retinitis pigmentosa (RP) is an inherited retinal dystrophy leading to progressive loss of the photoreceptors and retinal pigment epithelium and resulting in blindness usually after several decades. "Biallelic truncating mutations in RDH11 cause a form of retinitis pigmentosa (RP) with delayed psychomotor development, learning difficulties, and distinct craniofacial and physical dysmorphologies (MIM 61610814)." (PMID 34848785, 2021). "An RDH11 knockout in mice did not affect the retinoid profiles when the mice adapted to dark conditions, but the deleterious mutations in the RDH11 gene caused a new syndrome with retinitis pigmentosa, which is an inherited degenerative disease in the retina that causes severe vision impairment." (PMID 29410696, 2018).
breast carcinoma (1 paper, 2021). "Furthermore, we generated an expression risk score for each of the breast cancer patients in the METABRIC Discovery, Validation and TCGA sets using the seven genes RDH5, RDH8, RDH10, RDH11, RDH12, RDH13, RDH14." (PMID 33436820, 2021). "To explore the expression patterns of the seven genes RDH5, RDH8, RDH10, RDH11, RDH12, RDH13, RDH14 in normal tissues as well as breast cancer tissue, we first drew a heat map of the expression levels of the genes across normal human tissues from GTEx portal." (PMID 33436820, 2021).
diabetes (1 paper, 2024). "For example, fasting or diabetes affects expression of genes involved in retinoic acid metabolism in the liver, with levels of RDH11 significantly downregulated." (PMID 39009342, 2024).
lung carcinoma (1 paper, 2025). "Additionally, ADH1B, ZNF300, GPR161, and RDH11 were presented as the novel regulatory genes in lung injury and lung cancer." (PMID 39940682, 2025).
retinal disease (1 paper, 2010). "known retinal disease genes (BEST1 [NM_004183], C1QTNF5 [NM_015645], CDH3 [NM_001793], LRAT [NM_004744], RDH5 [NM_002905], RDH11 [NM_016026], RGR [NM_002921], RLBP1 [NM_000326] and STRA6 [NM_022369])." (PMID 20479888, 2010).
sarcoma (1 paper, 2021). A usually aggressive malignant neoplasm of the soft tissue or bone. "Interestingly, the G2 subgroup mainly contained the sarcomas with elevated expression of RDH11, RDH8, RDH16, CYP2A6, and ALDH1A2, all of them were strongly or slightly correlated with poor survival." (PMID 35186946, 2021).
RDH11 also shares sentences with these, for which no sentence is quoted: cancer (3 papers); colon cancer (1); degenerative disease in the (1); dilated cardiomyopathy (1); geographic atrophy (1); human papillomavirus infection (1); rectum adenocarcinoma (1); tumor (1); Usher syndrome (1).